METTL3 (methyltransferase 3, N6-adenosine-methyltransferase complex catalytic subunit)
Diseases named in the same sentence as METTL3 in open-access papers (continued):
Sharing a sentence is not in itself a finding about the gene and the disease.
cancer (continued). "To further investigate the effect of METTL3 on EMT, we treated cells with 10 ng/mL TGFβ1, which has been considered to be the major EMT inducer in cancer cells." (PMID 31991845, 2020). "In CRC, METTL3 facilitates CRC self-renewal and increases stem cell frequency by preventing the mRNA degradation of SOX2, a cancer stem cell marker." (PMID 32429972, 2020). "Implications of METTL3, METTL14, FTO, ALKBH5, and YTHDF2 have been demonstrated in several types of cancer such as acute myeloid leukemia, hepatocellular cancer, and glioblastoma." (PMID 33273988, 2020). "METTL3 and IGF2BP2 are key genes in the m6A signal pathway and have recently been shown to play important roles in cancer development and progression." (PMID 33224879, 2020). "Based on the existing results, METTL3 and METTL14 control cancer cell fate through cell growth- and cell death-related pathways." (PMID 32765970, 2020). "METTL3, METTL14 and RBM15 expression are all upregulated in AML compared with other types of cancer." (PMID 32513173, 2020). "Recently, the mRNA methylation complex containing METTL3, METTL14, and WTAP has been the subject of intense study in human cancers." (PMID 33133142, 2020). "Methyltransferase-like enzyme 3 (METTL3) and methyltransferase-like enzyme 14 (METTL14) are two major enzymes involved in m6A modifications that play vital roles in various cancers." (PMID 32765970, 2020). "Methyltransferase-like 3 (METTL3) is a member of the m6A methyltransferase family and acts as an oncogene in cancers." (PMID 33059689, 2020). "In conclusion, DRG1 exerted cancer-promoting effects on OS, and up-regulated DRG1 in OS was induced by METTL3 and ELAVL1 in an m6A-dependent manner." (PMID 32266933, 2020). "Mechanistically speaking, METTL3 targets the suppressor of cytokine signaling 2 (SOCS2), a cancer suppressor, and increases the m6A level of it." (PMID 32612834, 2020). "Despite many of the studies on m6A performed in AML focused on coding RNAs, the METTL3/METTL14 and METTL16 methyltransferases can also modify non-coding transcripts with relevant role in cancer, such as lncRNAs and circular RNAs (circRNA)." (PMID 31024852, 2019). "Earlier studies have revealed the critical role of m6A regulators, particularly METTL3, METTL14, FTO and ALKBH5 in driving cancer progression and metastasis." (PMID 31069256, 2019). "Here, we will focus on therapeutic strategies and small molecules targeting the METTL3/METTL14 complex and discuss their potential applications in cancer treatment." (PMID 31024852, 2019). "The clinical relevance of this pathway is increasingly evident, as aberrant expression of m6A regulators such as METTL3, FTO, ALKBH5, or IGF2BPs correlates with poor prognosis, advanced disease stage, therapy resistance and immune evasion, in multiple cancer types." (PMID 41228380, 2025). "Finally, current drugs targeting m6A mainly focus on METTL3 and FTO, with research predominantly centred on cancer." (PMID 39779466, 2025). "METTL3‐mediated m6A modification weakens cilia elongation by enhancing HDAC6 expression, leading to a shortening of cilia length and ultimately accelerating cell proliferation and cancer progression." (PMID 39535388, 2025). "METTL3 (Methyltransferase 3, N6-Adenosine-Methyltransferase Complex Catalytic Subunit) plays a key role in a variety of cancers, either dependent or independent of its m6A RNA methyltransferase activity." (PMID 39941003, 2025). "DBH‐AS1 is upregulated by METTL3‐mediated m6A modification, and overexpression of DBH‐AS1 sponges miR‐3163 and upregulates the expression of USP44, a target gene of miR‐3163, thereby reducing gemcitabine resistance and suppressing cancer growth." (PMID 40448344, 2025). "Furthermore, METTL3 facilitates the m6A modification of pyruvate dehydrogenase kinase 4 (PDK4), increases PDK4 mRNA translation, stimulates cancer cell glycolysis, and subsequently promotes the growth and progression of CC." (PMID 40356909, 2025).
cancer (continued). "Furthermore, combining METTL3 and PARP inhibitors led to an enhanced antiproliferative effect on cancer cells." (PMID 40219966, 2025). "Targeting METTL3/METTL14 for degradation reduces m6A levels and inhibits cancer cell proliferation." (PMID 41446042, 2025). "The METTL3/ADAR1 axis establishes a connection between m6A modification and A‐to‐I RNA editing during posttranscriptional regulation, which reveals a novel pathway involved in cancer progression." (PMID 39802639, 2025). "m6A regulators include writers (METTL3, METTL14, KIAA1429, and ZC3H13), erasers (ALKBH5 and FTO) and readers (YTHDF1/2/3, IGF2BP1/2/3), which are thought to play important roles in regulating cancer progression." (PMID 40774945, 2025). "Additionally, METTL3 was also found to enhance the translation of oncogenes EGFR and TAZ in cancer cells by directly recruiting the translation initiation factor elf3, independent of its catalytic activity or any m6A readers." (PMID 40136363, 2025). "Additionally, STM2457, a METTL3/METTL14 inhibitor, exhibited potent antileukemic effects in preclinical AML models, highlighting the feasibility of targeting m6A writers for cancer therapy." (PMID 40565233, 2025). "Co-transfection of METTL3 and SLC7A11 constructs showed that SLC7A11 overexpression attenuated METTL3-induced fluorescence intensity of C11-BODIPY and reduced sensitivity to erastin in METTL3-overexpressing cancer cells." (PMID 39800682, 2025). "Moreover, both in vitro and in vivo data suggest that METTL3/SLC7A11 is involved in m6A regulated growth and erastin sensitivity of cancer cells." (PMID 39800682, 2025). "m6A modification by METTL3 stabilizes FBXO31 mRNA by binding to YTHDF1, which increases FBXO31 expression and promotes proteasome‐dependent degradation of sirtuin 2 (SIRT2), leading to cancer progression." (PMID 40448344, 2025). "The MTase domain of METTL3 is critical for cancer growth, with key motifs (DPPW, IHM, RTGRTGH) that are central to its carcinogenic effects; DPPW acts as a catalytic motif, while RTGRTGH is crucial for the MTase activity of the METTL3-METTL14 complex." (PMID 39791162, 2025). "This approach offers a more targeted and potentially effective strategy for treating cancers where cytoplasmic METTL3 enhances oncogenic translation without relying on its enzymatic activity." (PMID 38444581, 2024). "Elevated METTL3 has been seen in NSCLC and is involved in cancer progress." (PMID 38688909, 2024). "In recent years, accumulated evidence has shown that METTL3 plays a crucial role in various types of cancer, depending on or independent of its m6A RNA methyltransferase activity." (PMID 38281945, 2024). "METTL3‐mediated m6A modification of microRNAs miR‐100 and miR‐125b are enriched in EVs secreted from the cetuximab‐resistant CRC cells, which upon exposure to non‐resistant cancer cells exhibit resistance to cetuximab." (PMID 39661414, 2024). "UZH2 is a small molecule inhibitor that selectively targets METTL3 and reduces the m6A levels of polyadenylated RNA in the MOLM-13 (acute myeloid leukemia) and PC-3 (prostate cancer) cell lines and has great potential as a therapeutic agent for cancer." (PMID 39229278, 2024). "STC-15, a derivate of STM2457, is a METTL3 inhibitor that has been reported to reduce acute myeloid leukaemia (AML) cell growth and increase survival in in vivo AML mouse models, with similar results identified in other cancer cell lines." (PMID 39033689, 2024). "METTL3 could methylate BCL-2 and c-Myc mRNAs to increase their stability and expression, thus suppressing cancer cells apoptosis, and promoting disease progression." (PMID 38589454, 2024). "Alternative strategies, such as PROteolysis TArgeting Chimeras (PROTACs) targeting METTL3 may offer a solution to overcome the limitations of current small molecular inhibitors of METTL3 in the treatment of AML and other cancers." (PMID 40453361, 2024).
cancer (continued). "Intriguingly, METTL3 and POU5F1 (Oct4) were reported to affect miR‐1246 levels in cancer cells." (PMID 38342611, 2024). "Although previous studies have well-established the function of METTL3 in human cancers, including OSCC, whether METTL3 has a regulatory role in OSCC CSCs still needs further elucidation." (PMID 38355684, 2024). "Despite its potential safety as a cancer patient supplement, the lack of selectivity for METTL3 suggests the need for further optimization." (PMID 38545841, 2024). "Additionally, a study observed a correlation between METTL3 expression and the splicing factor SRSF11 in several cancer types, including breast invasive ductal carcinoma, lung adenocarcinoma, CRC, and GC." (PMID 39767561, 2024). "Because the METTL3 has been documented to function in many types of cancers, modulating its LLPS behavior may be a potentially critical facet for inhibiting cancer progression." (PMID 39006762, 2024). "In myeloid cells, METTL3 activates the NF-κB pathway and STAT3 signaling, leading to M1 and M2-like polarization of macrophages, and fosters the proliferation and spread of cancer cells, contingent upon the infiltration of M1 and M2 phenotype-like TAMs, and maintains YTHDF1-mediated SPRED2." (PMID 39372415, 2024). "Consequently, the response to anti-PD-1 therapy is enhanced, highlighting the potential of METTL3 and METTL14 as therapeutic targets for anti-cancer immunotherapy." (PMID 39136000, 2024). "SOCS2 is shown to be regulated by METTL3 and YTHDF2 in various cancers." (PMID 39600630, 2024). "METTL3 and METTL14 may thus be a potential prognosis marker and a therapeutic target in certain types of cancers." (PMID 39006762, 2024). "In addition, the deletion of METTL3 and overexpression of ALKBH5 resulted in suppression of the in vitro migration, invasion, and EMT of cancer cells." (PMID 39136000, 2024). "A large number of studies of m6A regulatory mechanisms have investigated classical m6A regulators, such as METTL3, METTL14, WTAP, METTL16, FTO, ALKBH5, YTH family proteins, and IGF2BPs; anti-cancer target drugs targeting METTL3 and FTO have been proven to be effective against cancer." (PMID 38970366, 2024). "Further, STM2475, the first-in-class non-nucleoside Mettl3 inhibitor, has demonstrated its efficacy in the treatment of malignant tumors in vitro, which is an exciting achievement in the field of Mettl3 research." (PMID 37007040, 2023). "METTL3 and METTL14 participate in the maturation of primary (pri-)miRNAs such as miR-25-3p, pri-miR221/222, pri-miR-1246, pri-miR-375 and pri-miR-126 in different cancers." (PMID 37202385, 2023). "With the help of the established CRISPR/dCas13 system to accurately edit the m6A modification platform, it is proved that the METTL3-HMBOX1 axis regulates telomere recruitment and telomere length related to telomerase in cancer cells, and leads to DNA damage reaction." (PMID 37519297, 2023). "On the contrary, in colorectal cancer, METTL3-mediated m6A modification enhances the binding of circALG1 to miR-342-5p, thereby upregulating placental growth factor (PGF) expression, which accelerates cancer cell metastasis." (PMID 38125749, 2023). "Extensive evidence obtained in recent years has revealed that METTL3 plays key roles in various types of cancer, either dependent or independent of its m6A RNA methyltransferase activity." (PMID 36550779, 2023). "METTL3 was elevated in GEM-resistant PC cells, and its downregulation inhibited cancer progression." (PMID 37915034, 2023). "Current studies have uncovered that as reduced‐miRNAs failed to target METTL3 in diverse cancers, augmented METTL3 elevated proliferative‐correlative proteins and signalling pathways in a miRNAs‐METTL3‐related way." (PMID 36162823, 2023). "Elevated METTL3 strengthened the m6A levels of APC mRNA in esophageal squamous cell carcinoma and subsequently recruited YTHDF to degrade APC mRNA, ultimately activating cancer cell proliferation and aerobic glycolysis." (PMID 37344779, 2023).
cancer (continued). "Furthermore, the analysis revealed correlations between METTL3 expression and the expression of immune cell-related genes, such as CD8 + T cell, regulatory T cells, and macrophages, in various cancer types, particularly in LIHC." (PMID 38012755, 2023). "The gene HMGA2 codes a non-histone architectural TF that positively regulates the EMT process in a series of fibrotic diseases (type 2 EMT) and cancer metastasis (type 3 EMT), which might be the main target of METTL3 in EMT of RPE cells." (PMID 36945110, 2023). "SP1 is a METTL3 target that regulates c-MYC expression and plays oncogenic roles in cancer." (PMID 39872957, 2023). "Surprisingly, an obvious decrease in JAK1 and STAT3 expressions was also observed in METTL3 knockdown cancer cells, but not in control groups." (PMID 38001065, 2023). "Accordingly, METTL3 is a candidate target for the treatment of CRC and other cancers." (PMID 37965577, 2023). "In LIHC cancer cell Huh7 xenografts, knockdown of METTL3 or treatment with STM2457 resulted in decreased m6A modification and up-regulated expression of DUSP5 and SPRY2, suggesting that METTL3 suppression has a repression effect on the MAPK cascades." (PMID 38012755, 2023). "One gene found to interact with RBMX was methyltransferase-like 3 (METTL3), an oncogene that could promote translation of cancer cell proteins." (PMID 36077923, 2022). "Currently, m6A protein machineries found in cervical cancer including METTL3, YTHDF1 and FTO all play a role in promoting the occurrence of cancer, and whether other machineries are involved in CC can be explored in the future." (PMID 35813486, 2022). "One possible reason is that METTL3 plays a reader role in some types of cancer, which is independent of methyltransferase activity." (PMID 36226062, 2022). "Therefore, silence METTL3 can reduce the expression of SOX2, which further enhance the sensitivity of cancer cells to γ-irradiation." (PMID 35022030, 2022). "Our present study is the first to demonstrate that quercetin could inhibit METTL3 and decrease the m6A/A ratio in MIA PaCa-2 cells, which provides a base for targeted treatment of diseases, especially cancer." (PMID 35571106, 2022). "Then, we focus on the role of WTAP in cancers either dependent or independent of METTL3-METTL14 methyltransferase and summarize the specific mechanisms of WTAP in tumorigenesis and development." (PMID 36207306, 2022). "Recently, increasing evidence has suggested that METTL3 plays a key role in many human cancers, either dependent or independent of its m6A RNA methyltransferase activity." (PMID 35794583, 2022). "One study found that METTL3 but not FTO is significantly increased in cancer tissues, whereas the other study found that both were significantly increased." (PMID 35155557, 2022). "Therefore, targeting METTL3 alone should consider the results of the action triggered by METTL14, and the interaction between METTL14 and METTL3 is also a potential target for cancer therapy." (PMID 36226062, 2022). "Increased levels of m6A and METTL3 were found in 5-FU resistant CRC cells, and targeted inhibition or knockdown of METTL3 could inhibit glycolysis in cancer cells and restore chemo-sensitivity to 5-FU in resistant CRC cells." (PMID 36778600, 2022). "An increasing number of studies have confirmed that m6A writers (METTL3, METTL14, KIAA1429, WTAP), erasers (FTO and ALKBH5) and readers (YTHDC1, YTHDC2, YTHDF1, YTHDF2 and HNRNPC) have distinct functions within different types of cancer cells." (PMID 35042525, 2022). "Therefore, METTL3 is important for the growth and survival of EBV-positive cancer cells during the EBV lytic cycle." (PMID 35783391, 2022). "However, the diverse functions and mechanisms of METTL3 in CRC progression, as well as other cancers, need further studies." (PMID 35273176, 2022).
cancer (continued). "Taken together, these findings highlight the complicated roles of m6A regulators in macrophages and suggest that METTL3/14 and YTHDF2 may be potential targets for cancer immunotherapy." (PMID 35296338, 2022). "Moreover, it was found that the expression levels of METTL3 and IGF2BP3 were higher in cancer tissues than those in adjacent tissues." (PMID 36276112, 2022). "METTL3, methyltransferase 14, N6-adenosine-methyltransferase complex catalytic subunit (METTL14) and YTH N6-methyladenosine RNA binding protein 1/2 (YTHDF1/2) are m6A modifiers in human NSCLC and play oncogenic roles in this cancer." (PMID 35441574, 2022). "Furthermore, ablation of METTL3 disrupts the autocrine action of TGF-β1 by interrupting TGF-β1 dimer formation and TGF-β1-induced EMT in cancer cells." (PMID 34616742, 2021). "However, overexpression of METTL3 and METTL14 has also been indicated to suppress cancer cell growth." (PMID 33611339, 2021). "Overall, our data disclose the novel molecular pathway METTL3/ADAR1/CDK2 connecting m6A and ADAR deaminases that can strongly change the scenario of post-transcriptional events with important consequences in cell homeostasis, differentiation, and cancer field." (PMID 33509238, 2021). "In addition to chemicals targeting METTL3, recent research progress has shown the potential of limiting SAM levels, ncRNAs and programmable m6A-editing systems in m6A methyltransferase-based cancer treatment." (PMID 34315512, 2021). "METTL3 acts on the reader IGF2BP2, and IGF2BP2 directly binds to a specific m6A site of in SOX2 CDS and controls the half-life of SOX2 mRNA by relying on m6A modification to produce cancer-promoting effects." (PMID 34246319, 2021). "High expression of METTL3 in LUAD is believed to promote the growth and invasion of cancer cells." (PMID 34416861, 2021). "METTL3 and METTL14 expression have been reported to promote tumourigenesis in several cancer types." (PMID 33461542, 2021). "Interestingly, opposite regulatory roles of METTL3 and METTL14 were observed in some cancers including HCC." (PMID 34046411, 2021). "In addition, some biotech or pharmaceutic companies get down to developing high-efficiency small-molecule inhibitors, targeting the m6A regulators, in particular molecules like METTL3 and FTO that vary significantly in many cancers." (PMID 35004679, 2021). "As the Wnt/β-Catenin pathway is a complex signaling cascade, the identification of novel genes in the Wnt/β-Catenin pathway, such as METTL3 and METTL14, might provide additional therapeutic opportunities in cancer treatment." (PMID 34315512, 2021). "Collectively, these in vitro and in vivo results strongly support that METTL3 may act as an oncogene and promote tumorigenesis in both cSCC and HNSCC and highlight the potential of targeting aberrant RNA methylation for cancer therapy." (PMID 34298617, 2021). "Next, we detected the METTL3 expression pattern in cancer tissues and normal paracancerous tissues from 60 ESCA patients and the results of qRT-PCR revealed an markedly elevated METTL3 expression pattern in ESCA tissues compared to the normal paracancerous tissues (P < 0.001)." (PMID 34666602, 2021). "Like METTL3, FTO also plays pro- and antitumor roles in cancer." (PMID 34616742, 2021). "In this review, we summarize recent progress in understanding the function and regulation of different m6A methyltransferase complexes, with a main focus on the METTL3-METTL14-WTAP complex, in the core signaling pathways of cancers and their roles in therapeutic resistance." (PMID 34315512, 2021). "We demonstrated that YTHDF bound METTL3-mediated m6A of APC mRNA and reduced APC expression, revealing a previously unknown mechanism by which the Wnt/β-catenin pathway is upregulated in cancer in an epitranscriptomal regulation-dependent manner." (PMID 34155197, 2021).